NSA2 (NSA2 ribosome biogenesis factor)
Description:
Involved in the biogenesis of the 60S ribosomal subunit. May play a part in the quality control of pre-60S particles (By similarity).
Synonyms: TINP1; HUSSY-29; HCLG1; FLJ94393; CDK105; HCL-G1; HUSSY29
Tractability: Small molecule: a structure with a bound ligand is known. PROTAC: UniProt records ubiquitination sites on it; ubiquitination databases record sites on it; its protein half-life has been measured.
Gene: Protein-coding gene on chromosome 5 (74,766,991 to 74,780,113, forward strand). Ensembl gene ENSG00000164346.
Subcellular location: Nucleus, nucleolus
Subcellular location (Human Protein Atlas): Nucleoli; Nucleoplasm
Gene Ontology:
Molecular function: RNA binding
Biological process: maturation of 5.8S rRNA; maturation of LSU-rRNA
Cellular component: nucleolus; nucleoplasm; preribosome, large subunit precursor
Genetic constraint (gnomAD): Loss-of-function variants: 16 observed, 26.72 expected, observed/expected ratio (o/e) 0.6, 90% interval 0.4 to 0.91. The upper end of that interval is the gene's LOEUF score, 0.91, which puts it in group 3 of 6, group 1 being the genes least tolerant of losing a copy. Missense variants: 157 observed, 249.65 expected, observed/expected ratio (o/e) 0.63, 90% interval 0.55 to 0.72. Synonymous variants: 69 observed, 79.46 expected, observed/expected ratio (o/e) 0.87, 90% interval 0.71 to 1.06.
Homologues: Orthologues: guinea pig NSA2 (100% identical), chimpanzee NSA2 (99% identical), macaque NSA2 (99% identical), mouse Nsa2 (99% identical), rat Nsa2 (99% identical), tropical clawed frog nsa2 (98% identical), zebrafish nsa2 (95% identical), Drosophila melanogaster Ip259 (75% identical), Caenorhabditis elegans W09C5.1 (70% identical).
Diseases named in the same sentence as NSA2 in open-access papers:
NSA2 is named in the same sentence as 15 diseases in open-access papers, as found by Europe PMC text mining. Sharing a sentence is not in itself a finding about the gene and the disease. The quoted sentences say what the papers report.
diabetic nephropathy (2 papers, 2019 to 2024). "We previously reported aberrant expression of the cytosolic ribosomal biogenesis factor Nop-7-associated 2 (NSA2) in diabetic nephropathy, the latter also known to involve mitochondrial dysfunction, however the connections between NSA2, mitochondria and renal disease were unclear." (PMID 39396937, 2024). "However, the underlying mechanisms that contributed to NSA2 up-regulation in diabetes and diabetic kidney disease, and the impact of this on the kidney or cellular function remained unknown." (PMID 39396937, 2024). "Recently, NSA2 has been reported as the candidate gene for diabetic nephropathy and is related to the TGF-β1 pathway." (PMID 31455417, 2019).
Alzheimer disease (1 paper, 2019). A progressive, neurodegenerative disease characterized by loss of function and death of nerve cells in several areas of the brain leading to loss of cognitive function such as memory and language. "A previous study has demonstrated that NSA2 is activated after permanent middle cerebral occlusion in an Alzheimer’s disease mouse model; NSA2 was predicted to be related to brain defense and tissue repair in the pathological process of Alzheimer’s disease." (PMID 31275757, 2019).
ANE syndrome (1 paper, 2016). "Thus, the presence of the ANE syndrome mutation (L306P) disrupts Nop4 interaction with a subset of Nop4’s interacting proteins (Mak5, Nop4, Nsa2 and Noc2) by Y2H, suggesting that the ANE syndrome mutation disrupts Nop4 function as a hub protein in the LSU processome." (PMID 27077951, 2016).
cervical carcinoma (1 paper, 2017). A carcinoma arising from either the exocervical squamous epithelium or the endocervical glandular epithelium. "Over-expression of the NSA2 protein promotes cell growth and regulates the G1/S transition in the cell cycle in different cell lines including HeLa (human cervical carcinoma), HEK293T (human embryonic kidney) and A549 (human epithelial lung adenocarcinoma)." (PMID 28316886, 2017).
chondropathies (1 paper, 2019). "NSA2 was the most significant gene identified by TWAS for chondropathies, also detected by the mRNA expression profiling of knee OA cartilage." (PMID 31455417, 2019).
chronic kidney disease (1 paper, 2024). Impairment of the renal function secondary to chronic kidney damage persisting for three or more months. "In the current paper, we show that NSA2 expression is co-regulated with the GTP-dependent ribosome recycling factor mitochondrial 2 (GFM2) and provide a molecular link between cytosolic and mitochondrial ribosomal biogenesis with mitochondrial dysfunction in chronic kidney disease (CKD)." (PMID 39396937, 2024).
hyperglycaemia (1 paper, 2024). "To understand the potential mechanisms by which hyperglycaemia could regulate renal NSA2 expression and contribute to the mechanistic changes that lead to CKD, we evaluated potential genetic regulators of the human NSA2 gene in the current study." (PMID 39396937, 2024).
Lyme disease (1 paper, 2016). Lyme disease (named after the towns in the USA where the disease was first identified) is a bacterial infection caused by Borrelia burgdorferi. "While no DEGs were identified on the basis of single versus multiple lesions, four DEGs were found to be upregulated in seronegative Lyme disease patients relative to those who were seropositive, namely, HLA-DQA1, HLA-DQB1, HLA-DRB5, and NSA2." (PMID 26873097, 2016).
Sepsis (1 paper, 2025). Sepsis is defined as life-threatening organ dysfunction caused by a dysregulated host response to infection.
cancer (3 papers, 2019 to 2025). A tumor composed of atypical neoplastic, often pleomorphic cells that invade other tissues. "However, the role of NSA2 in cancer development remains obscure." (PMID 40076615, 2025). "Four riboSNitch-depleted 5′UTRs (ING3, RBM22, NSA2 and TAF2) were detected at the q-value cutoff of 0.05, and all of these elements were cancer-specific." (PMID 31160636, 2019).
tumor (2 papers, 2022 to 2025). "Together, these data suggest that 9c exerts its anti-tumor effects mainly through inhibition of the NSA2-EGFR signaling pathway." (PMID 40076615, 2025). "NSA2 is highly expressed in a variety of tumor cells, such as A549 and HepG2 cells." (PMID 40076615, 2025).
kidney disease (1 paper, 2024). "Our data link the regulation of 2 highly conserved genes, NSA2 and GFM2, connected to ribosomes in two different cellular compartments, cytosol and mitochondria, to kidney disease and shows that their dysregulation may be involved in mitochondrial dysfunction." (PMID 39396937, 2024).
NSA2 also shares sentences with these, for which no sentence is quoted: diabetes (1 paper); infection (1); ovarian carcinoma (1).